RAD51AP2 (RAD51 associated protein 2)
Synonyms: FLJ17540
Tractability: PROTAC: ubiquitination databases record sites on it.
Gene: Protein-coding gene on chromosome 2 (17,510,579 to 17,518,440, reverse strand). Ensembl gene ENSG00000214842.
Subcellular location (Human Protein Atlas): Nucleoli; Cytosol; Mitotic chromosome
Gene Ontology:
Molecular function: protein binding
Cellular component: protein-containing complex
Genetic constraint (gnomAD): Loss-of-function variants: 61 observed, 76.71 expected, observed/expected ratio (o/e) 0.8, 90% interval 0.65 to 0.98. The upper end of that interval is the gene's LOEUF score, 0.98, which puts it in group 4 of 6, group 1 being the genes least tolerant of losing a copy. Missense variants: 1,201 observed, 1,270.9 expected, observed/expected ratio (o/e) 0.95, 90% interval 0.9 to 0.99. Synonymous variants: 445 observed, 430.65 expected, observed/expected ratio (o/e) 1.03, 90% interval 0.95 to 1.12.
Homologues: Orthologues: chimpanzee RAD51AP2 (98% identical), macaque RAD51AP2 (90% identical), pig RAD51AP2 (61% identical), rabbit RAD51AP2 (58% identical), dog RAD51AP2 (51% identical), rat Rad51ap2 (50% identical), mouse Rad51ap2 (45% identical).
Diseases named in the same sentence as RAD51AP2 in open-access papers:
RAD51AP2 is named in the same sentence as 2 diseases in open-access papers, as found by Europe PMC text mining. Sharing a sentence is not in itself a finding about the gene and the disease. The quoted sentences say what the papers report.
cholangiocarcinoma (1 paper, 2023). A carcinoma that arises from the intrahepatic biliary tree (intrahepatic cholangiocarcinoma) or from the junction, or adjacent to the junction, of the right and left hepatic ducts (hilar cholangiocarcinoma). "TH, IGDCC3, RAD51AP2, and MUC2 are genes that were identified by WGCNA and are related to the clinical prognosis and survival of cholangiocarcinoma, but they have already been reported." (PMID 36979826, 2023).
tumor (2 papers, 2023 to 2025). "Another tumor (TCGA-CI-6624) had a contribution of 28% of SBS8, with two somatic missense variants in BRCA2 of unknown pathogenic effect, as well as one each in RAD51AP2 and BRCC3." (PMID 41194282, 2025). "Furthermore, we identified eight hub genes (VSNL1, TH, PCP4, IGDCC3, RAD51AP2, MUC2, BUB1, and BUB1B) that promoted tumor progression and were associated with prognosis according to the Kaplan–Meier and ROC curve analyses." (PMID 36979826, 2023).